HNF4A (hepatocyte nuclear factor 4 alpha)
Diseases named in the same sentence as HNF4A in open-access papers (continued):
Sharing a sentence is not in itself a finding about the gene and the disease.
tumor (continued). "Both confluent and proliferating HepaFH3 cells (HepaFH3 C and HepaFH3 P) showed a statistically significant reduction in albumin, hepatocyte nuclear factor 4 alpha (HNF4A), and cytochrome P450 3A4 (CYP3A4) expression compared to non-HCC-PHHs isolated from tumor-free liver tissue." (PMID 40862732, 2025). "This is the first study that correlates HNF4A expression with patient survival in PDAC and most importantly the expression is assessed following scoring of immunostained tissues and not relying on bulk tumor profiling." (PMID 39165427, 2024).
cancer (177 papers, 2006 to 2026). A tumor composed of atypical neoplastic, often pleomorphic cells that invade other tissues. "In the context of cancer, HNF4α is implicated in essential processes, such as differentiation, proliferation, invasion, migration, and apoptosis." (PMID 40277924, 2025). "Studies show HNF4α expression as a potential diagnostic tool to distinguish between primary cancers and metastases." (PMID 37635981, 2023). "Cell invasion was closely associated with the downregulation of HNF4A expression, which promotes cancer metastasis." (PMID 36866237, 2023). "HNF4A is a nuclear transcription factor, which is highly expressed in most cancers and is significantly associated with poor prognosis." (PMID 34434660, 2021). "High-throughput analysis of cancer cell genomes has established that hotspot mutations in HNF4α and HNF1α occur in a variety of human cancers, including liver, renal, colorectal, and pancreatic carcinomas (ICGC Database)." (PMID 34771521, 2021). "Among non-coding RNAs associated with cancer, of particular attention is miR-122, the most frequently detected miRNA in the liver and a direct target of HNF4α." (PMID 34771521, 2021). "Aberrant expression of HNF4α is a characteristic of several types of cancer, and altered expression of HNF4α is strongly associated with the clinical outcome." (PMID 33462379, 2021). "The first one, HNF4A, is involved in several forms of cancer and implicated in the formation of progenitor cells from stem cells." (PMID 34941772, 2021). "In conclusion, HNF4α has long been recognized as an important regulator of differentiation and is currently associated with cancer." (PMID 33462379, 2021). "The link between HNF4α and various cancers can be used to predict the susceptibility of tumors to treatment." (PMID 33462379, 2021). "HNF4α is linked to several human diseases including diabetes, hepatitis B viral infection, and cancer." (PMID 31695151, 2020). "Other research groups have shown HNF4α plays a critical role in inflammation-associated cancers and exhibits certain organ specificity." (PMID 26870992, 2016). "Recent emerging research has demonstrated that HNF4α may serve as a novel diagnostic and prognostic biomarker and an effective target for cancer therapy." (PMID 37338793, 2023). "Research has shown that HNF4α acts as an oncoprotein that converges on genes encoding anti-apoptotic oncogenes and cytokines and may promote cancer development." (PMID 37338793, 2023). "Interestingly, the upregulation of HNF4α in cancer cells has been shown to be strongly associated with tumorigenesis suppression via induction of differentiation." (PMID 36132168, 2022). "The presence of abnormal HNF4α expression may provide a diagnostic and prognostic biomarker for certain cancers." (PMID 33462379, 2021). "We hypothesize that one aspect may be due to declining transcriptional translation levels of the downstream genes associated with cancer caused directly by HNF4a or that HNF4a reverses the abnormal proliferation and differentiation of cells directly." (PMID 33628089, 2021). "The reduced expression of HNF4A has been associated with tumorigenesis in various cancers." (PMID 32774369, 2020). "Since evidence has suggested that loss of p21 or p27 function may contribute to cancer cell chemoresistance, we subsequently explored the relationship between HNF4α and gemcitabine sensitivity." (PMID 30867652, 2019). "The exact association between HNF4a and cancers remains unclear." (PMID 33628089, 2021).
cancer (continued). "Collectively, a large body of evidence shows that HNF4α is associated with the proliferation, differentiation, progression, and metastasis of cancer cells, which could be considered potential prognostic and diagnostic biomarkers during the development of cancer." (PMID 33462379, 2021). "Moreover, HNF4α may serve as a novel diagnostic and prognostic biomarker and an effective target for cancer therapy." (PMID 33462379, 2021). "Additionally, the identification of HNF4α and HNF1α as mutated targets in cancer suggests that systematic searches through cancer cell genomes for somatic mutations will ultimately provide a full picture of the pathophysiology and therapeutic opportunities for underlying human oncogenesis." (PMID 34771521, 2021). "HNF4A (hepatocyte nuclear factor 4 alpha) is a ligand activated nuclear transcription factor that regulates the expression of many genes involved in lipid transport and glucose metabolism and are associated with cell cycle, immunity, apoptosis, stress response and cancer." (PMID 23874591, 2013). "Hepatocyte nuclear factor 4 alpha (HNF4A), a member of the nuclear receptor family, has been implicated in various aspects of cancer development and progression." (PMID 41326348, 2025). "Due to this dual function, selective HNF4α modulators are under investigation as potential cancer therapies." (PMID 40926269, 2025). "HNF4α was recently shown to be involved in the growth and invasion of various cancers as oncoprotein." (PMID 38710944, 2025). "HNF4α also has a role as an oncoprotein and is involved in carcinogenesis, cancer growth, and invasion in various cancers such as hepatocellular cancer, colorectal cancer, gastric cancer, and Barret’s esophageal cancer." (PMID 38710944, 2025). "The only transcription factor whose expression and activity were downregulated in ccRCC was HNF4A, which directly controls genes critical for PT function again suggesting dedifferentiation in ccRCC cancer cells." (PMID 39792555, 2025). "Nur77 (NR4A1) and HNF4α (Hepatocyte Nuclear Factor 4 Alpha) further contribute to BCa biology by regulating gene expression in cancer cells." (PMID 40806474, 2025). "In HCC, the loss of HNF4α disrupts epithelial identity and promotes epithelial-to-mesenchymal transition (EMT), a process that enhances cancer cell invasiveness, proliferation, chemoresistance, and metastatic potential." (PMID 40926269, 2025). "Strategies include context-specific small-molecule inhibitors or activators, and epigenetic therapies that reprogram HNF4α target gene expression depending on cancer subtype and cellular environment." (PMID 40926269, 2025). "The expression patterns and functions of HNF4α vary significantly across different types of cancers." (PMID 40277924, 2025). "Ongoing research into HNF4α modulators offers exciting potential for improving cancer therapies and metabolic health." (PMID 40926269, 2025). "HNF4A is expressed widely in cancers of the gastrointestinal tract, biliary tree, and pancreas as opposed to HNF6, encoded by the ONECUT1 gene, whose expression is restricted to liver and small bile duct carcinomas." (PMID 41425714, 2025). "Another cyclin gene, CCNE1 also showed a trend for higher amplification frequency in ELF3/HNF4A up-regulated cancers (Student’s t-test p = 0.06)." (PMID 41425714, 2025). "Transwell migration and invasion assays were employed to validate the impact of HNF4α regulation on cancer cell behavior." (PMID 40277924, 2025). "Extensive insights into the expression and regulatory mechanisms of HNF4α in cancer progression and metastasis should enhance our understanding of its clinical significance." (PMID 40277924, 2025). "In the liver metastatic foci, DKK2 knockout rescued HNF4A protein levels followed by reduction of lysozyme positive cancer cells." (PMID 38659853, 2024). "Integration of HNF4A cancer-specific methylation and expression data identified promoter methylation as the driving force of HNF4A suppression." (PMID 39165427, 2024).
cancer (continued). "Analysis of the HNF4A locus revealed cancer-specific hypermethylation in the promoter and gene body regions." (PMID 39165427, 2024). "HNF4α is a promising therapeutic target in a variety of cancers via the regulation of various signaling pathways (i.e., Wnt/β-catenin, NF-κB, STAT3, TGFβ)." (PMID 39199690, 2024). "Third, integration of the HNF4A cancer-specific methylation with expression data, both in tissues and cell lines, demonstrated that the methylation status of the proximal promoter region inversely correlates to gene expression." (PMID 39165427, 2024). "The activation of NF-κB signaling by IL1β/IL1R1 leads to the upregulation of HNF4α, establishing a feedback loop that sustains NF-κB pathway activation and propels inflammation towards cancer development." (PMID 38372868, 2024). "First, we observed that cancer stem cell markers expression is higher in PANC-1 HNF4A expressing spheroids when compared to the respective adherent cells." (PMID 39165427, 2024). "Mutation analysis revealed elevated mutation rates for IDH1, HNF4A, and ATF4 in LGG, UCEC, and SKCM, as well as higher mutation rates for this ferroptosis-cancer co-associated gene." (PMID 37304867, 2023). "In this model, nuclear HNF4A expression was evident in cancer cells (albeit weak expression), whereas HNF4G and Btnl1 expressions were lost from tumors." (PMID 37309673, 2023). "HNF4A was found to induce carcinogenesis and the development of cancers, according to several studies." (PMID 37180584, 2023). "As a gene therapy tool for HCC, forced re-expression of HNF4A inhibits proliferation and eliminates cancer-specific features of target cells." (PMID 37333982, 2023). "Recently, some studies demonstrated that HNF4α is involved in the proliferation, apoptosis, invasion, and migration of cancer cells both in vitro and in vivo." (PMID 37338793, 2023). "Apart from HCC, CRC, and GC, HNF4α has been shown to have significant role in many other cancer types." (PMID 36249028, 2022). "We used HNF4α as hepatic marker and clone formation ability as tumorigenicity marker to evaluate success of cancer cell differentiation." (PMID 35343115, 2022). "HNF-4α plays a pivotal role in cholesterol metabolism, but it is also involved in the proliferation, invasion, and migration of cancer cells." (PMID 36430456, 2022). "Consistently, based on the matched RNA-seq samples, we found HNF4A was expressed almost exclusively in these cancer types." (PMID 35227282, 2022). "Here, we review the role and the mechanism of HNF4α in various cancers, try to emphasize the importance of HNF4α in tumorigenesis and look forward to helping with the treatment and prevention of cancer." (PMID 36249028, 2022). "Nonetheless, a preponderance of evidence points to the fact that the role of HNF4α in cancer is not only isoform-specific but also depends on the status of HNF4α gene amplification." (PMID 34771521, 2021). "Uncovering the role of HNF4α in inflammation is a crucial area of research and can offer new therapeutic options for inflammation-driven cancers." (PMID 34771521, 2021). "Hnf4a expression resulted in a decreased expression of cancer-promoting factors LSD1, SETD1A, PRMT1, FOXM1, FAK, and SNAI1, and also an increased expression of CDH1." (PMID 34595169, 2021). "By developing highly specific small molecules that can selectively target the diseased cell, HNF4α will offer new therapeutic options for cancer treatment." (PMID 34771521, 2021). "Recently, additional emerging studies demonstrated that HNF4α is involved in the proliferation, apoptosis, invasion, and migration of cancer cells both in vitro and in vivo." (PMID 33462379, 2021). "HNF4A was also correlated with the pathogenesis of different cancers, and it was known that HNF4A was down‐regulated by the AMPK energy‐sensing kinase." (PMID 34309216, 2021). "Occasionally, HNF4A was found to be upregulated in gastrointestinal adenocarcinomas and promote the cancer as shown by knockdown assays." (PMID 34595169, 2021).
cancer (continued). "HNF4α has been found to influence signaling pathways involved in cancer induction and progression in early-stage liver and colorectal cancers." (PMID 33462379, 2021). "Various studies have documented that aberrant expression of HNF4α is a potential cancer-specific signature and can be correlated with clinical features in malignant tissues, indicating an important role of HNF4α in several types of cancer." (PMID 33462379, 2021). "As a member of the nuclear receptor superfamily of transcription factors, HNF4α has been reported to possess enormous potential as a clinical therapeutic target in several types of cancer." (PMID 33462379, 2021). "The expression levels of HNF4a in the twenty different malignant tumors were related to different prognoses." (PMID 33628089, 2021). "Additional therapeutic drugs can be designed based on the characteristics of HNF4α, especially for the treatment of cancer." (PMID 33462379, 2021). "Taken together, these results indicate that there is extensive interaction between HNF4α and TGFβ during cancer progression." (PMID 33462379, 2021). "We identified cancer-relevant genes (ING1, ARL4C) whose expression between patients is influenced by enhancer differences in genomic copy number and germline SNPs, and HNF4α as a master trans-acting factor associated with GC enhancer heterogeneity." (PMID 34635154, 2021). "Abnormal expression of HNF4α is emerging as a critical factor in cancer cell proliferation, apoptosis, invasion, dedifferentiation, and metastasis." (PMID 33462379, 2021). "Expression of HNF4α forms an HNF4α-STAT3 feedback regulatory loop that regulates the course of carcinoma." (PMID 33462379, 2021). "Despite an attractive potential for pharmacological interventions in diabetes or cancer, the collection of ligands that can modulate the transcriptional activity of HNF4α is scarce." (PMID 33114319, 2020). "In line with its expression being increased in GIAC, inhibition of HNF4A signaling suppressed the growth of GIAC cancer cells and xenografts." (PMID 32998360, 2020). "In contrast to the numerous studies investigating HNF4A’s role in cancer, little is known regarding HNF4G." (PMID 32998360, 2020). "The ligand-activated transcription factor HNF4α has been found to involve in metabolic balance and cancer development, but, to date, knowledge on its ligands is very limited." (PMID 33114319, 2020). "The downregulation of mir-24-3p can assist this process by deactivating the Fas receptor in the NOTCH pathway and inhibiting HNF4A to drive a feedback loop that leads to cancer-related inflammatory reaction." (PMID 33424926, 2020). "Further illustrating that cancer relies on processes involved during development, the reciprocal downregulation between HNF4A and SNAIL is at play both in liver stem cells and in HCC." (PMID 32998360, 2020). "Hepatocyte nuclear factor 4α (HNF4α) is a ligand-sensing transcription factor and presents as a potential drug target in metabolic diseases and cancer." (PMID 33114319, 2020). "HNF4α exhibits high expression in the adult liver, kidney, intestine, pancreas, and some cancer cell lines derived from these organs." (PMID 31695151, 2020). "Although there is abundant evidence that HNF4α plays an important role in hepatic development, its role in the regulation of tumorigenesis and cancer development has been less widely studied." (PMID 30867652, 2019). "HNF4α is a TF that takes part in two distinct feedback loops that occur in normal and cancer cells, respectively, consisting of IL-6R; the miRNAs miR-24, miR-124, and miR-629; and STAT3." (PMID 31557902, 2019). "By using NGS technologies, somatic mutations in several novel cancer-related genes such as ARID1A (7.53%), HNF4α (0.88%), FAT4 (4.71%) and IRF2 (1.06%) have been identified and suggested to be associated with HCC." (PMID 31395065, 2019).